INS (insulin)
Diseases named in the same sentence as INS in open-access papers (continued):
Sharing a sentence is not in itself a finding about the gene and the disease.
Hyperinsulinemia (continued). "However, it should be emphasized that the markedly increased CS in the AT cells in T2D is unlikely to be a consequence of hyperinsulinemia alone, as insulin levels were not higher in the matched T2D individuals compared with the obese nondiabetic individuals." (PMID 37317964, 2023). "Since hyperinsulinemia plays a crucial role in the development and clinical presentation of PCOS, it is essential to acknowledge that plasma insulin levels reflect both the insulin secretion rate from beta cells and the metabolic clearance rate of insulin (MCRI) from plasma." (PMID 36834549, 2023). "Also, basal hyperinsulinemia in cattle is a result not of a reduced insulin body catabolism, but a higher glucose-induced insulin secretion rate which is potentiated in estrus." (PMID 36626404, 2023). "Therefore, we hypothesize that TNF-α is a potential inducer to deteriorate hyperinsulinemia and subsequent T2DM by promoting β cell mass and insulin secretion." (PMID 35198097, 2022). "However, chronic treatment with olanzapine induced islet hyperplasia and hyperinsulinemia, and also inhibited insulin secretion in pancreatic islets from female mice without interfering with serotonin metabolism or Ca2+ signaling in beta cells." (PMID 35629947, 2022). "Interestingly, the compensatory hyperinsulinemia was mainly sustained by a reduction of hepatic insulin clearance rather than a net increased insulin secretion." (PMID 35979433, 2022). "In fact, the lack of effect of metformin on fasting blood glucose in our study may represent the “floor effect”, whereas the correction of hyperinsulinemia without change in glucose suggested an improvement in insulin sensitivity." (PMID 35574481, 2022). "Although currently there is no direct evidence demonstrating the risk of insulin in initiating PDA in genetic mutation carriers and family history, the activation of insulin signal pathway and circulating hyperinsulinemia elevated the cancer risk in mutated gene carriers." (PMID 35252207, 2022). "Our results showed that postnatal overfeeding could be a critical factor that leads to decreased systemic insulin sensitivity and consequent hyperinsulinemia in the animal model of PCOS, still not accompanied by impaired insulin signaling in the VAT." (PMID 36012206, 2022). "In addition, studies on rodent models of hyperinsulinemia (obese mice) and hypoinsulinemia (streptozotocin-treated rats) demonstrated that the concentration of insulin in the central nervous system (CNS) was independent of peripheral insulin levels." (PMID 35741464, 2022). "However, these insulin-mediated effects appeared dose-dependent since the HPA axis was only clearly stimulated during hyperinsulinemia but not when insulin was administered in physiological concentrations." (PMID 35897752, 2022). "While physiological insulin concentrations probably help to maintain a functional tissue macrophage phenotype and to support PI3K-dependent inhibitory feedback loops that limit a pro-inflammatory response to PAMPs or DAMPs, hyperinsulinemia appears to enhance the effect of pro-inflammatory stimuli." (PMID 35955975, 2022). "However, in our study, the increase in prandial InsExt in the first 10–20 min was shared during meal studies with and without hyperinsulinemia induced by exogenous insulin infusion." (PMID 35887007, 2022). "However, in the current study we did not observe hyperinsulinemia; insulin was not significantly higher in T2DM rats compared to their age-matched healthy controls at any stage." (PMID 36703927, 2022). "Likewise, we previously showed that PT failed to protect against developing hyperinsulinemia and additionally had no impact on muscle insulin sensitivity or bodyweight increase." (PMID 36145121, 2022).
Hyperinsulinemia (continued). "As shown, serum insulin levels were significantly higher at ZT15 in both male (one-way ANOVA; F(Firoc; control) = 9.21654; p = 0.01616) and female mice (one-way ANOVA; F(Firoc; control) = 12.43179; p = 0.01681), indicating that Firoc mice develop hyperinsulinemia, at least during the active phase." (PMID 35563069, 2022). "On the other hand, it has also been suggested that the absence of FoxOs may mimic some conditions of hyperinsulinemia, because FoxOs are exquisitely sensitive to very low levels of insulin." (PMID 35104242, 2022). "In males, the effects of hyperinsulinemia on PanIN development are less clear: despite a trend toward lower PanIN plus tumor area in the pancreata of males with reduced Ins2 gene dose, PanIN plus tumor area did not correlate with insulin levels." (PMID 35189981, 2022). "Although insulin does not cross the placental barrier, maternal hyperinsulinemia may exert effects on the placenta allowing for increased fetal nutrient uptake." (PMID 36329895, 2022). "Reduced insulin sensitivity, which is often observed in persons with NAFLD, may boost hepatic fat accumulation by increasing free fatty acid release from adipose tissue, and by the effect of hyperinsulinemia on anabolic processes." (PMID 36336684, 2022). "Moreover, postprandial hyperinsulinemia during an OGTT in obese NAFLD individuals has been shown to strongly correlate with reduced hepatic insulin clearance but not insulin secretion." (PMID 33498493, 2021). "Hyperinsulinemia may play an important role in the development of non-alcoholic fatty liver disease (NAFLD) because of the relationship between insulin response and body fat accumulation." (PMID 34221261, 2021). "Recently, it also has been reported that impaired insulin clearance and hyperinsulinemia could occur in non-obese Asians." (PMID 33935964, 2021). "By improving insulin sensitivity, increasing the production of glucose transporter-4 (GLUT-4) and lowering visceral adipose tissue, physical activity may further contribute to an improvement in hyperinsulinemia." (PMID 34360563, 2021). "As insulin is not endogenously regulated, insulin enters the system from the injection site, and not via the portal vein with first pass by the liver, and so peripheral tissue experiences relative hyperinsulinemia." (PMID 33897473, 2021). "Furthermore, an inverse correlation between the CD3+CD4+/CD3+CD8+ ratio and DI values, reflecting insulin sensitivity were found, and increased CD3+CD4+/CD3+CD8+ is an indicator for hyperinsulinemia, revealing the involvement of CD3+CD4+/CD3+CD8+ in RPL patients with IR." (PMID 33935964, 2021). "Hyperinsulinemia and impaired insulin processing seen in hIAPP mice lacking ZnT8 suggests that a similar hypersecretion of hIAPP along with impaired hIAPP processing may have contributed to the increased amyloid accumulation in these animals." (PMID 34027899, 2021). "However, the challenge remains to identify agents that selectively inhibits hyperinsulinemia without affecting normal insulin secretion." (PMID 33911083, 2021). "As metformin reduces peripheral hyperinsulinemia in vivo, the drug might be able to counteract the observed negative insulin effects when administered to patients with high levels of the pancreatic hormone." (PMID 33690729, 2021). "To assess whether differences in TT and FT concentrations between clinical subgroups are related to degree of hyperinsulinemia and SHBG levels, we compared fasting insulin and SHBG, where available, in patients aged >10 years with lipodystrophy, insulin signaling defects or idiopathic SIR." (PMID 33901270, 2021). "Here, we hypothesized that the T2D disease pattern can be achieved by combining a HFD and a low‐dose streptozotocin (STZ) treatment, designed to cause mild hyperglycemia (a condition similar to prediabetes) based on insulin resistance (because of the feeding of a HFD for 4 weeks, hyperinsulinemia)." (PMID 33103024, 2020).
Hyperinsulinemia (continued). "To investigate whether insulin lowers ANGPTL4 expression in vivo, we extracted data from a transcriptomics dataset of adipose tissue biopsies from human subjects before and after 3 h intravenously maintained euglycemic hyperinsulinemia." (PMID 32504883, 2020). "Although hyperinsulinemia may increase uptake in muscles, there seems to be no known association of colonic FDG uptake with insulin." (PMID 32815120, 2020). "Therefore, SCGN is related to insulin secretion and hyperinsulinemia during pregnancy; however, it does not display differences between women with NGT and GDM." (PMID 32708966, 2020). "Insulin-stimulated phosphorylation of FOXO1 is reduced, expression of PEPCK and G6Pase genes remains elevated, but the lipogenic SREBP1c pathway remains sensitive to insulin, nuclear SREBP1c levels increase with hyperinsulinemia and this worsens triglyceridemia." (PMID 32455838, 2020). "Also as in humans, plasma lipid concentrations were low, and insulin-stimulated hepatic lipogenesis was not increased despite hyperinsulinemia." (PMID 32439336, 2020). "We postulate, therefore, that hyperleptinemia in cirrhosis is a consequence of hyperinsulinemia, but that this is driven, at least in part by hepatocellular dysfunction and abnormal portosystemic shunting of insulin, and not (just) by the natural history of the illness or an increase in adiposity." (PMID 32092909, 2020). "In agreement with its gene expression profile, adiponectin secreted levels were not affected by hyperinsulinemia in both the cell types (198 ng/ml in untreated vs 199 ng/ml in insulin-treated 3T3-L1, p = 0.911; 113 ng/ml in untreated vs 95 ng/ml insulin-treated SGBS, p = 0.086)." (PMID 32718202, 2020). "Thus, PEGyAMPH treatment prevents the development of hyperinsulinemia and improves glucose homeostasis by increasing peripheral insulin sensitivity without suppressing secretion." (PMID 32402266, 2020). "In addition, some patients with clinical evidence of hyperinsulinism do not have very elevated insulin levels." (PMID 31840185, 2020). "However, the relationship between CH and hyperinsulinism is unproved in this syndrome since increased insulin levels were not reported in most patients with CH." (PMID 31840185, 2020). "Nevertheless, subjects with meal-triggered hypoglycemic response had higher postprandial insulin and C-peptide excursions, without altered insulin sensitivity or beta-cell function, thus, reinforcing the role of hyperinsulinism, with peak levels 2-times higher, as the central mechanism of PBH." (PMID 33424773, 2020). "Therefore, despite causing defective IR endocytosis in the liver, SHP2 inhibition led to a mild defect in insulin clearance, but not severe hyperinsulinemia as observed in the CEACAM1 KO mice." (PMID 30931927, 2019). "Pre-treatment of cells with metformin prevented insulin-induced increases in H3K9 acetylation, indicating the potential significance of using metformin in triple-negative breast cancer patients with hyperinsulinemia to prevent insulin-mediated chromatin changes." (PMID 31315653, 2019). "Interestingly, the faLA group had an improvement in HOMA-IR due to a small reduction in fasting hyperinsulinemia, however, this occurred despite no improvement in hepatic steatosis or insulin signaling based on hepatic pAkt." (PMID 31022865, 2019). "This is important when determining the type of DM on which intervention is planned, as type I would benefit from insulin increase, and type II, due to hyperinsulinemia, may not." (PMID 31810205, 2019). "Interestingly, long term consumption of sucralose produced hyperinsulinemia followed by sucrose or SV, whereas those fed brown sugar, honey, SG, or no sweetener had the lowest serum insulin." (PMID 31010163, 2019). "As HFD-fed and STZ-injected mice are characterized by hyperinsulinemia and insulinopenic state, respectively, it is important to understand whether the presence or absence of insulin affects the expression of LCN2." (PMID 30761088, 2019).
Hyperinsulinemia (continued). "Unfortunately, despite the occurrence of hyperinsulinemia that might be supposed in the obese patients, insulin serum levels were not measured or reported." (PMID 31174276, 2019). "Interestingly, and as showed by others these changes in subcutaneous adipose tissue seem to be independent of systemic insulin levels, given that in our study exercise did not reverse hyperinsulinemia." (PMID 31105582, 2019). "Indeed, clinical data support the beneficial effects exerted by inositol by reducing glycaemia levels and hyperinsulinemia and buffering negative effects of sustained insulin stimulation upon the adipose tissue and the endocrine system." (PMID 30595691, 2018). "Interestingly, hyperinsulinemia could increase TCF7L2 mRNA expression, and subjects with low insulin sensitivity had higher TCF7L2 mRNA expression in skeletal muscle tissue." (PMID 29713286, 2018). "Supporting these facts, in previous studies, our working team has demonstrated that metforminium decavanadate produces metabolic regulation on carbohydrates and lipids in hyperinsulinemia and hypoinsulinemia models, regardless of the insulin-mimetic action by vanadium." (PMID 30026756, 2018). "In contrast, when we analyzed glucose homeostasis we found that male Nnat+/–p mice displayed a defect in GSIS in vivo compared with WT littermates, with the complete absence of an increase from basal insulin levels, as well as unexpected basal hyperinsulinemia." (PMID 29864031, 2018). "Interestingly, the serious glycaemic impairment courses with hyperinsulinemia in T2DM mice, a profile not observed in humans, in whom the loss of glycaemic control only appears when plasma insulin levels start to decrease." (PMID 28708105, 2017). "The present study design would be strengthened with an additional exercise session with a 3 hour post exercise muscle sample in the absence of hyperinsulinemia, to allow for a more robust comparison of the specific effects of insulin on transient changes in mitochondrial function after exercise." (PMID 29161316, 2017). "In the PLG group, this effect of insulin may be absent due to the short term exposure to hyperinsulinemia." (PMID 26790104, 2016). "However, while a long-term HFD caused hyperinsulinemia in Flox/Flox animals but not M4K4 iKO mice, acute S961 treatment induced both plasma insulin as well as C-peptide levels to a similar extent in both genotypes." (PMID 27226575, 2016). "Results from the subgroup analysis according to fasting insulin level also showed that M values in individuals with fasting hyperinsulinemia were lower than those without fasting hyperinsulinemia, confirming that waist circumference and FINS were predictors of IR levels." (PMID 26770991, 2016). "Insulin and IGF have been shown to accelerate the growth of endometrial cancer cells in vitro, and the mitogenic effect of hyperinsulinemia may be mediated by activation of the mitogen-activated protein kinase (MAPK) pathway, increasing expression of vascular endothelial growth factor (VEGF)." (PMID 26770659, 2016). "Collectively, our data suggest that hyperinsulinemia, independent of impaired insulin action, may contribute to endothelial dysfunction by favoring the predominance of vasoconstrictor signaling." (PMID 27796268, 2016). "Moreover, this study serves as a first step toward changing the prevailing concepts about hyperinsulinemia, which may promote reevaluation of the current therapeutic approaches for T2DM such as insulin secretagogues and administration of exogenous insulin." (PMID 27796268, 2016). "Campia and coworkers demonstrated that acute hyperinsulinemia impairs conduit vessel endothelial function independent of insulin sensitivity and lipid profile concluding that hyperinsulinemia may trigger ED and promote atherosclerosis too." (PMID 26089897, 2015).
Hyperinsulinemia (continued). "Blocking the effects of hyperinsulinemia in ob/ob mice by knocking down the insulin receptor further induced FMO3 protein, consistent with the notion that the signaling pathways utilized by insulin to suppress Fmo3 become partially resistant to insulin in ob/ob mice." (PMID 25849138, 2015). "Therefore, there is no absolute definition of hyperinsulinemia, since an insulin level that is raised for an individual is usually still within the wide range of normality." (PMID 25834745, 2015). "Since insulin/IGF-1 receptors are expressed in epidermal keratinocytes, hyperinsulinemia may lead to an increased proliferation of basal keratinocytes within the FPSU duct inducing failure of terminal differentiation of follicular corneocytes, thus actively participating in acne pathogenesis." (PMID 25977937, 2015). "The mechanism by which an elevated or prolonged exposure to insulin (referred to here as hyperinsulinemia, regardless of origin) exerts its deleterious effects on insulin signaling remains unclear." (PMID 25259572, 2014). "The first major trial concerning the use of metformin and/or insulin during pregnancies complicated with GDM was the metformin in gestational diabetes (MiG), whose goal was to determine the effects of either drug on prevention of fetal hyperinsulinemia and promotion of lower maternal glycemia." (PMID 25763406, 2014). "Thus, glucagon seems to exert a positive modulatory effect on insulin secretion under basal glucose concentrations in DEX rats, and this action may be involved in the fasting hyperinsulinemia observed after GC treatment." (PMID 24705399, 2014). "Furthermore, although insulin sensitivity was not measured in these animals, analysis of fasting insulin levels indicated that prenatal dexamethasone treatment resulted in hyperinsulinemia." (PMID 24886466, 2014). "While such studies reveal a clear negative effect of hyperinsulinemia on insulin action, they do not elucidate the mechanism by which this process occurs so that it may be avoided." (PMID 25259572, 2014). "However, the impact of marked hyperinsulinemia on the healthy heart, which was demonstrated not to be insulin-resistant at the time of examination, by a lack of down-regulation of GLUT4 expression, is reported here for the first time." (PMID 25101057, 2014). "Additionally, fibrotic pancreatitis was identified on pathomorphological examination as a potential reason for the lack of insulin production in destroyed pancreatic islets and hyperinsulinemia." (PMID 25202394, 2014). "In hyperinsulinemia, the amount of this soluble receptor increases and this could lead to higher amounts of insulin bound to this receptor, rather than free insulin, which is the biologically active form of the hormone." (PMID 24995000, 2014). "The down-regulation of TLR4 combined with the lack of increased production of pro-inflammatory cytokines (i.e., IL-6 and TNF-α) and SOCS3 following insulin infusion in the current study suggested that hyperinsulinemia exerts an anti-inflammatory effect on the heart in non-obese individuals." (PMID 25101057, 2014). "Thus, GPR40 knockout mice have a lower insulin level and would not develop hyperinsulinemia compared to normal mice on HFD-treatment." (PMID 23776696, 2013). "A therapeutical alternative could be the use of antidiabetic insulin sensitizers (e.g., thiazolidinediones) that, under hyperinsulinemia, would decrease insulin availability to the brain without affecting glycemia." (PMID 22500228, 2012). "Second, since hyperinsulinemia or IR may either induce hyperleptinemia or promote the selective downregulation of the HMW adiponectin forms, a different degree of insulin sensitivity in the adipose cells may well have contributed to the impaired secretion of these adipokines." (PMID 21365005, 2011).